FAM47E-STBD1 (FAM47E-STBD1 readthrough)
Gene: Protein-coding gene on chromosome 4 (76,251,721 to 76,311,129, forward strand). Ensembl gene ENSG00000272414.
Genetic constraint (gnomAD): Loss-of-function variants: 31 observed, 35.81 expected, observed/expected ratio (o/e) 0.87, 90% interval 0.65 to 1.17. The upper end of that interval is the gene's LOEUF score, 1.17, which puts it in group 5 of 6, group 1 being the genes least tolerant of losing a copy. Missense variants: 380 observed, 423.13 expected, observed/expected ratio (o/e) 0.9, 90% interval 0.82 to 0.98. Synonymous variants: 167 observed, 164.65 expected, observed/expected ratio (o/e) 1.01, 90% interval 0.89 to 1.15.